TRPM8 (transient receptor potential cation channel subfamily M member 8)
Diseases named in the same sentence as TRPM8 in open-access papers (continued):
Sharing a sentence is not in itself a finding about the gene and the disease.
breast carcinoma (37 papers, 2010 to 2025). "In breast cancer, TRPM8 expression is hormone dependent as steroid deficiency induced a decrease in TRPM8 mRNA." (PMID 37033630, 2023). "Similarly, TRPM8-promoted cell migration and invasion in breast cancer cells are associated with phosphorylation of AKT and GSK-3β, as well as changes in the levels of E-cadherin, fibronectin, vimentin, and SNAIL." (PMID 26512697, 2015). "TRPM7 is overexpressed in poorly differentiated and highly proliferative breast cancer, while TRPM8 is mainly overexpressed in highly differentiated and poorly proliferative breast cancer." (PMID 39633507, 2024). "Similar to TRPM8 expression in PCa cells which is regulated by androgens, TRPM8 expression levels are regulated by estrogens in breast cancer cells and correlate with ER+ status." (PMID 39633507, 2024). "In colon, oral, esophageal, bladder, and breast cancers, TRPM8 seems directly involved in invasiveness and metastasis via the regulation of the epithelial–mesenchymal transition process (EMT)." (PMID 37892239, 2023). "TRPM8 was also reported to be overexpressed in breast carcinoma, having a positive correlation with the mitotic (Ki67) index and the Scarff–Bloom–Richardson grade." (PMID 37240443, 2023). "In addition, expression of TRPM8 may be increased and is associated with larger tumor size, especially in breast carcinoma tissues, and TRPM8 is expressed more often in basal type breast cancers compared with the expression in other subtypes." (PMID 37435447, 2022). "Intriguingly, TRPM8 appears to have opposite functions according to the tumor type; it is overexpressed in breast cancers and its silencing leads to reduced tumor growth." (PMID 35847920, 2022). "TRPM7 and TRPM8 has proved act as oncogenes in breast cancer tissues compared with normal tissues, and is correlated with the Scarff-Bloom-Richardson (SBR) grade, Ki67 and tumor size." (PMID 36064388, 2022). "Although restricted to a limited number of studies, TRPM8 involvement in tumor progression has also been investigated in breast cancer since it was found overexpressed in human Breast Ductal Adenocarcinoma (hBDA) samples." (PMID 34831222, 2021). "TRPMs have also been recognized as important modulators in multiple cancers progression, from which TRPM2, TRPM7, and TRPM8 have been shown to promote breast cancer development." (PMID 32211326, 2020). "TRPM8 expression is up-regulated in several common human cancers, including prostate, lung, and breast cancer." (PMID 32929340, 2020). "The members of TRPM ion channel family such as TRPM2, TRPM7 and TRPM8 play vital roles in the growth, survival and metastasis of breast cancer cells, while somatic mutations affecting TRPM6 occur in breast cancer patients." (PMID 32484822, 2020). "Previous studies showed that TRPM8 is significantly upregulated in several types of cancer cells, including breast cancer cells, and promotes their proliferation and migration." (PMID 33344232, 2020). "Overall, autophagy is involved in TRPM8-depedent regulation of the proliferation and migration of breast cancer cells." (PMID 33344232, 2020). "In breast cancer, TRPM8 is significantly overexpressed, and pharmacological inhibition of TRPM8 decreases cell viability and migration of breast cancer cells." (PMID 31519770, 2019). "In breast cancer, TRPM8 promotes the aggressiveness of breast cancer cells by regulating epithelial-mesenchymal transition (EMT) via the activation of the AKT/GSK-3β pathway." (PMID 29772843, 2018). "In particular, TRPM8 has been found to be over-expressed in breast carcinoma, neuroblastoma, and osteosarcoma, as compared with the corresponding normal tissues." (PMID 26512697, 2015). "In prostate and breast carcinoma, expression of TRPM8 is regulated by androgen and estrogen, respectively." (PMID 26512697, 2015).
breast carcinoma (continued). "Taken together, we can suggest that in breast cancer, TRPM8 is functional at the plasma membrane and expressed in the early primitive breast cancers presenting a well-differentiated status." (PMID 20482834, 2010). "In the present study, we examined the expression and function of TRPM8 in the ER+ human breast cancer cell line MCF-7." (PMID 20482834, 2010). "Taken together, these results show that TRPM8 channels are expressed and functional in breast cancer and that their expression is regulated by ER alpha." (PMID 20482834, 2010). "The present study aimed at investigating the expression, function and potential regulation of TRPM8 channels by ER alpha (estrogen receptor alpha) in breast cancer." (PMID 20482834, 2010). "To confirm ERα regulation of TRPM8 in a physiological context, we studied the correlation between the over-expression of TRPM8 and ERα expression on breast cancer tissues samples." (PMID 20482834, 2010). "Taken together, these results suggest a hormonal-dependent regulation of TRPM8 expression in breast cancer." (PMID 20482834, 2010). "In conclusion, we have shown that TRPM8 is expressed and functional in breast cancer MCF-7 cell line." (PMID 20482834, 2010). "The expression of TRPM8 is upregulated in grade I adenocarcinomas of ER + breast cancer." (PMID 40078961, 2025). "Furthermore, TRPM8 is dependent on proliferation for autophagy and migration of breast cancer cells." (PMID 40078961, 2025). "Additionally, TRPM8 can improve the migration and proliferation of breast cancer cells by encouraging autophagy." (PMID 39633507, 2024). "Additionally, TRPM8 is linked to EMT markers such as E-cadherin, fibronectin, and vimentin, which play roles in the migration and invasion of breast cancer cells." (PMID 39633507, 2024). "Estradiol has been demonstrated to regulate TRPM8 channel expression in breast cancer cell lines." (PMID 37033630, 2023). "Moreover, autophagy mediates breast cancer proliferation and migration by regulating TRPM8 expression and activity." (PMID 37033630, 2023). "In addition, in pancreatic cancer and breast cancer, there were shown changes in Ras expression induced by TRPM8 activity." (PMID 37033630, 2023). "In addition, wound healing and transwell assays demonstrated that high expression of TRPM8 promotes a fast movement and invasive ability in breast cancer cells." (PMID 37033630, 2023). "TRPM8 was also found to control breast cancer angiogenesis, but in a Ca2+-independent manner." (PMID 36430727, 2022). "Interestingly, it was shown that overexpression of TRPM8 induced EMT in breast cancer cells by upregulating vimentin and fibronectin while downregulating E-cadherin." (PMID 34360952, 2021). "TRPM8 expression was upregulated in breast cancer cell samples." (PMID 34360952, 2021). "Furthermore, the regulatory effects of TRPM8 on the proliferation and migration of breast cancer cells are dependent on autophagy." (PMID 33344232, 2020). "Additionally, ATG7 knockdown impaired an increase in the migration of MDA-MB-231 cells transfected with TRPM8, suggesting that autophagy mediates the effect of TRPM8 on the migration of breast cancer cells." (PMID 33344232, 2020). "Finally, basal autophagy mediates the regulatory effects of TRPM8 on the proliferation and migration of breast cancer cells." (PMID 33344232, 2020). "Moreover, we report that expression changes in NOX2 and TRPM8 are correlated with poor clinical prognosis, which suggests disruption of this mechanically-activated pathway in breast cancer patients in vivo." (PMID 33020304, 2020). "Except TRPM7, TRPM8 has also been reported to modulate EMT in breast cancer cells." (PMID 32211326, 2020). "Thus, this study identifies TRPM8 as a novel regulator of basal autophagy in cancer cells acting by interacting with AMPK, which in turn activates AMPK to activate ULK1 in a coordinated cascade of TRPM8-mediated breast cancer progression." (PMID 33344232, 2020).
breast carcinoma (continued). "Autophagy has opposing, context-dependent roles in cancer and impacts the development of local recurrence after therapy failure; thus, autophagy may mediate the regulation of proliferation and migration by TRPM8 in breast cancer cells." (PMID 33344232, 2020). "Previous studies showed that TRPM8 enhances breast cancer cell migration by wound-healing assays." (PMID 33344232, 2020). "In addition, we found that TRPM8 was also up-regulated in gastric cancer cells, hepatocarcinoma cells, breast cancer cells and lung cancer cells." (PMID 31519770, 2019). "As a consequence, TRPM8 down-regulation in B-TECs is likely to accelerate vascular growth, thereby suggesting that TRPM8 activation (e.g., by icilin or menthol) could represent an efficient strategy to treat breast cancer." (PMID 32038296, 2019). "TRPM7 and TRPM8 expression was shown to be correlated with breast cancer." (PMID 29875336, 2018). "Moreover, expression of TRPM8 in breast carcinoma correlates with histological grade, Ki-67, tumor size, and expression of estrogen receptor." (PMID 26512697, 2015). "TRPM8 channels are expressed at both mRNA and protein levels in the breast cancer cell line MCF-7." (PMID 20482834, 2010). "Moreover, when analysing the expression of TRPM8 according to breast cancer grades, we found that TRPM8 is rather over-expressed in grade I (well differentiated) and II (moderately differentiated) than in grade III (poorly differentiated)." (PMID 20482834, 2010). "However, in breast cancer, the regulation of TRPM8 gene expression by putative estrogen response elements needs further investigations." (PMID 20482834, 2010). "Only a single report has mentioned the over-expression of TRPM8 mRNA in breast cancer." (PMID 20482834, 2010). "In the case of breast cancer, overexpression of TRPM8 has also been reported, which appears to be regulated by estrogen receptor alpha, and its expression levels are strongly correlated to proliferative parameters, hence making TRPM8 modulation strategies promising treatment alternatives." (PMID 35976012, 2022). "As a consequence, TRPM8 down-regulation in B-TECs is likely to accelerate vascular growth; this feature suggests that TRPM8 activation by icilin or menthol could represent an efficient strategy to treat breast cancer." (PMID 36430727, 2022). "In breast cancer cell lines, the authors hypothesized the formation through the cytoplasmic C-terminus of TRPM8 of a TRPM8-AMPK complex protein, which stimulates AMPK phosphorylation and activation, and subsequent the ULK1 activation to enhance basal autophagy." (PMID 36844925, 2022). "Finally, we investigated whether TRPM8 is over-expressed in human breast cancer tissues regarding their ER status." (PMID 20482834, 2010). "In breast cancer cells, the TRPV family and TRPM8 channels expression are regulated by β-estradiol and estrogen receptors." (PMID 32245175, 2020). "For example, TRPM8 was shown to activate the AKT–GST-3β pathway and regulate epithelial–mesenchymal transition (EMT) that promotes breast cancer metastasis." (PMID 33344232, 2020). "Silencing of TRPM8 decreases and over-expression increases the motility of MDA-MB-231 or MCF-7 breast cancer cells." (PMID 29772843, 2018). "Concerning TRPM8 channels, they are highly expressed at both the mRNA and protein levels in the MCF-7 breast cancer cell line, as well as in breast adenocarcinomas, and are especially correlated with estrogen receptor positive (ER+) tumors." (PMID 29875336, 2018). "TRPC1, TRPM7 and TRPM8 expression strongly correlated with proliferative parameters, and TRPV6 was mainly overexpressed in invasive breast cancer cells." (PMID 22692672, 2012). "However, in breast cancer, TRPM8 function and regulation by E2 are unknown." (PMID 20482834, 2010). "TRPM8 silencing reduces migration and invasion in MDA-MB-231 breast cancer cells." (PMID 40078961, 2025).
breast carcinoma (continued). "For example, TRPM8 activation may regulate AMPK activity by modifying cellular autophagy to control the proliferation and migration of breast cancer cells." (PMID 37892239, 2023). "In conclusion, we find that alterations in two major components of a mechanically-sensitive pathway identified in nontumorigenic MCF10A cells, NOX2 and TRPM8, are correlated with overall survival of ER− breast cancer patients." (PMID 33020304, 2020). "There are numerous studies showing a clear correlation between cancer patient survival and TRP channel expression, e.g., TRPC1, TRPM2 and TRPV4 in breast cancer, TRPM7 in PDAC, TRPM8 in bladder cancer and osteosarcoma and TRPV2 in breast and esophageal cancer to name just a few examples." (PMID 29772843, 2018). "The small proportion of responding cells suggest that TRPM8 channels are not widely functionally expressed in the MCF-7 breast cancer line." (PMID 20482834, 2010). "However, it has also been demonstrated that TRPM8 is not expressed in MDA-MB-231 cells, and the absence of TRPM8 transcripts was observed in half of the breast cancer cell lines examined." (PMID 40078961, 2025). "Furthermore, in vitro and clinical data support the role of TRPM8 as a biomarker for poor clinical outcome prediction in estrogen receptor (ER)-negative breast cancer patients." (PMID 34831222, 2021). "Further significance of this signaling pathway in cancer is highlighted by patient data which show that the combination of changes in NOX2/TRPM8 expression in estrogen receptor-negative (ER−) breast cancer patients is correlated with poor overall survival (hazard ratio, 2.4)." (PMID 33020304, 2020). "Moreover, we find that expression changes in both NOX2 and TRPM8 mRNA predict poor clinical outcome in estrogen receptor (ER)-negative breast cancer patients, a population with limited available treatment options." (PMID 33020304, 2020). "Assessment of the role of TRPM8, which was also positively correlated with NCS‐1, may be challenging given the absence of TRPM8 in many commonly used breast cancer cell lines." (PMID 31647602, 2020). "However, it has also been described that TRPM8 was not expressed in MDA-MB-231 cells and that the TRPM8 transcript is absent in half of the studied breast cancer cell lines, emphasizing that the relevance of TRPM8 as a therapeutic target is very limited in this case." (PMID 36844925, 2022). "Considering that TRPM8 is a non-selective Ca2+-permeable cation channel and plays a key role in calcium homoeostasis, we hypothesized that TRPM8 may control AMPK activity thus modulating cellular autophagy to regulate the proliferation and migration of breast cancer cells." (PMID 33344232, 2020).
melanoma (31 papers, 2010 to 2026). A malignant, usually aggressive tumor composed of atypical, neoplastic melanocytes. "In melanoma cells, one study demonstrated that activation of TRPM8 caused calcium influx and decreased cell viability." (PMID 37445615, 2023). "Mutated TRPM8 channels were identified in melanoma, which caused calcium channel dysregulation and subsequent downstream effects, including increased proliferation, uncontrolled growth, and dysfunctional apoptosis." (PMID 37445615, 2023). "However, in G-361 human melanoma cell line, menthol-mediated TRPM8 activity caused a prolonged increase in both the intracellular Ca2+ concentration and the amplitude of the current, drastically reduced the survival of melanoma cells." (PMID 29875336, 2018). "Strikingly, in this study the viability of melanoma cells was dose-dependently depressed in the presence of menthol, indicating that these channels underlie tumor progression via the Ca2+ handling pathway and suggesting TRPM8 Ca2+ channels as novel targets of drug development for malignant melanoma." (PMID 25710007, 2015). "The transient receptor potential melastatin 8 (TRPM8) ion channel is overexpressed in melanoma but its role as therapeutic target remains unexplored." (PMID 41688418, 2026). "We investigated the anti-tumor effects of novel TRPM8 modulators in metastatic melanoma cells using viability assays, apoptosis markers, mitochondrial function analyses, reactive oxygen species (ROS) measurements and gene silencing." (PMID 41688418, 2026). "TRPM8, a cold receptor, is of particular significance in the context of both melanocyte physiology and the development of melanoma." (PMID 40869148, 2025). "Among the oncogenic TRP isoforms, TRPM7, TRPV1, TRPV4, and TRPM8 have received considerable attention due to their frequent overexpression in melanoma cells and their functional contributions to the malignant phenotype." (PMID 40869148, 2025). "TRPM8 is functionally expressed in human melanoma cells, and its agonist, menthol, exhibits dose-dependent inhibition of melanoma cell viability." (PMID 39633507, 2024). "In malignant melanoma, activation of TRPM8 blocks the activation of vascular endothelial growth factor (VEGF) on TRPV1, thus inhibiting VEGF-induced neovascularization and melanoma growth." (PMID 38892000, 2024). "As previously discussed, other members of the TRPM subfamily (TRPM1, TRPM5, TRPM7, and TRPM8) appear to have essential roles in melanoma." (PMID 37445615, 2023). "Due to its expression in melanoma, the TRPM8 channel appears to be a novel target in the treatment of melanoma." (PMID 37445615, 2023). "TRPM8 expression increases in B16 melanoma cells after g-irradiation, which improves DNA damage response (DDR) for DNA repair and cell recovery." (PMID 37033630, 2023). "For relevance in cancer, TRPM8—initially thought to be expressed from a prostate-specific gene—was subsequently found in several other cancers, including melanoma." (PMID 37445615, 2023). "Radioresistance has been observed after radiation therapy, and TRPM8 contributes to the radioresistance of B16 melanoma cells." (PMID 37033630, 2023). "It was found that the highest mutation numbers were seen in UCEC, melanoma, and STAD, with TRPM8 representing approximately 7% of mutations." (PMID 35847920, 2022). "TRPM8 is a membrane receptor involved in the regulation of calcium ion influx and melanocytic behavior, and upregulated in melanoma." (PMID 32948083, 2020). "There are also numerous experimental evidences demonstrating that TRPM8 channels play important roles in tumor development and progression, including prostate, pancreas, breast, lung, colon, bladder and melanoma malignancies, among others." (PMID 32843690, 2020). "Menthol induced cytotoxicity was also pointed out in G-361 melanoma cells through a TRPM8-dependent mechanism only when using high doses of menthol, thus indicating a significant difference between A375 and G-361 cells in the sensitivity to menthol." (PMID 32948083, 2020).